INS (insulin)
Diseases named in the same sentence as INS in open-access papers (continued):
Sharing a sentence is not in itself a finding about the gene and the disease.
non-alcoholic fatty liver disease (continued). "However, high serum FGF21 levels are found in obese subjects, it can be increased in subjects with other insulin resistant states such as dyslipidemia and coronary artery disease non-alcoholic fatty liver disease (NAFLD) and polycystic ovarian syndrome." (PMID 27471739, 2016). "Elevated levels of plasmatic insulin may contribute to nonalcoholic fatty liver disease (NAFLD)." (PMID 36005626, 2022). "When plasma glucose levels are high, insulin, a hormone produced by pancreatic beta cells, inhibits gluconeogenesis under physiological conditions, but when peripheral tissues are resistant to insulin, gluconeogenesis in the liver increases, which leads to nonalcoholic fatty liver disease (NAFLD)." (PMID 34445384, 2021). "Nonalcoholic fatty liver disease (NAFLD), characterized by an excessive fat deposition in hepatocytes, excluding alcohol and other specific liver damaging factors, is an acquired metabolic stress liver injury closely related to insulin resistance and genetic predisposition." (PMID 33817272, 2020). "Therefore, a non-invasive way to assess the long-term consequences of insulin and lipid impairment could be done through the screening of non-alcoholic fatty liver disease (NAFLD, the hepatic manifestation of MES and IR), i.e., through the use of Fibroscan." (PMID 32733840, 2020). "The results show that a sugar-restricted diet reduces hepatic lipogenesis, fasting insulin levels, hepatic fat, and ALT in adolescents with non-alcoholic fatty liver disease (NAFLD)." (PMID 40525060, 2025). "MAFLD, formerly known as non-alcoholic fatty liver disease (NAFLD), shares several pathophysiological mechanisms with ALD but is mainly driven by metabolic imbalances, including excess caloric intake, insulin resistance, and altered adipose tissue function." (PMID 40722875, 2025). "Non-alcoholic fatty liver disease (NAFLD) is closely related to type 2 diabetes (T2D), with reduced insulin sensitivity being a key factor in their disrupted metabolic processes." (PMID 39911865, 2025). "In patients with non-alcoholic fatty liver disease (NAFLD), combining ADF with exercise for 3 months significantly reduced the intrahepatic triglyceride content and body weight, and improved the insulin sensitivity and glucose metabolism." (PMID 41536827, 2025). "Kyoto Encyclopedia of Genes and Genomes (KEGG) pathway analysis revealed significant enrichment in many pathways linked to glucolipid metabolism, such as PI3K‐Akt signaling, insulin signaling, IR, AMPK signaling, and nonalcoholic fatty liver disease." (PMID 39792613, 2025). "Previous studies have examined the impact of AT and Vit D on insulin, fasting blood glucose, and HOMA-IR in human subjects with T2D and elderly women with nonalcoholic fatty liver disease (NAFLD)." (PMID 38431555, 2024). "Nonalcoholic fatty liver disease (NAFLD) is a complex systemic disease that is characterized by hepatic lipid accumulation, lipotoxicity, insulin resistance, gut dysbiosis, and inflammation." (PMID 38084145, 2023). "Those genes of cluster 1 were related with the insulin signaling pathway, AMPK signaling pathway, and nonalcoholic fatty liver disease (NAFLD)." (PMID 35502176, 2022). "For example, two genes previously associated with non-alcoholic fatty liver disease, or NAFLD (COBLL1 and PNPLA3), show colocalization in the liver, the former with fasting insulin and BMI and the latter with T2D, HDL, and TG, implicating them as shared genetic associations for IR/T2D and NAFLD." (PMID 35292083, 2022). "Non-alcoholic fatty liver disease (NAFLD) is the most prevalent chronic liver disease worldwide and a metabolic condition in which fat accumulates in the liver related to insulin resistance." (PMID 35430797, 2022). "Concomitantly, the liver undergoes lipid accumulation (non-alcoholic fatty liver disease, NAFLD), which further disrupts the Fe balance due to an increase in the production of cytokines and insulin resistance." (PMID 33918997, 2021).
non-alcoholic fatty liver disease (continued). "Further, P. gingivalis decreased insulin sensitivity and increased pro-inflammatory cytokines TNF-α and IL-6, causing an inflammatory response in the liver by lipid droplet formation indicating that periodontitis may affect nonalcoholic fatty liver disease (NAFLD;)." (PMID 33504065, 2021). "A Low Glycaemic Index (LGI) diet is a proposed lifestyle intervention in non-alcoholic fatty liver diseases (NAFLD) which is designed to reduce circulating blood glucose levels, hepatic glucose influx, insulin resistance and de novo lipogenesis." (PMID 34620653, 2021). "Dietary habits and gut microbiota play an essential role in non-alcoholic fatty liver disease (NAFLD) and related factors such as insulin resistance and de novo lipogenesis." (PMID 34578867, 2021). "Thus, further studies are needed to investigate associations between those parameters and non-alcoholic fatty liver disease (NAFLD) markers to clarify whether NAFLD affects fasting insulin and UAE independent of glycemia, hypertension, and other confounders." (PMID 33003574, 2020). "High levels of NEFA, a pathological factor for nonalcoholic fatty liver disease (NAFLD), demonstrate lipotoxicity and can impair hepatic mitochondrial function and insulin signaling." (PMID 29882814, 2018). "Non-alcoholic fatty liver disease (NAFLD) is characterized by ectopic lipid accumulation in the liver, usually combined with hepatic insulin resistance." (PMID 30261661, 2018). "In another study, patients with T2DM and nonalcoholic fatty liver disease treatment with semisynthetic derivative of CDCA led to enhanced serum FGF19 levels and improved insulin sensitivity." (PMID 28729691, 2017). "In conclusion, FX improves glucose tolerance and insulin sensitivity, decreases lipogenesis and increases lipid oxidation in the liver of HFD rats, implying a potential application in the treatment of non-alcoholic fatty liver disease." (PMID 23585904, 2013). "This study aimed to analyze the effects of exercise at the aerobic/anaerobic transition on the markers of non-alcoholic fatty liver disease (NAFLD), insulin sensitivity and the blood chemistry of rats kept on a fructose-rich diet." (PMID 20946638, 2010). "In addition, losing weight decreases the hepatic TG content by decreasing de novo lipogenesis in patients with non-alcoholic fatty liver disease (NAFLD) and increasing circulating glucose and insulin." (PMID 39859502, 2025). "As for S100A6, a member of the S100 family of calcium-binding proteins, has been reported to be associated with T2DM development, contributing to hepato-pancreatic communication to reduce insulin production and promote the progression of T2DM in individuals with nonalcoholic fatty liver disease." (PMID 39850446, 2025). "Significant differences in the values of ALT, glucose at 2h-PH, fasting insulin, and indices of IR between obese children with and without nonalcoholic fatty liver disease have been documented by Polish authors." (PMID 39125447, 2024). "Non-alcoholic steatohepatitis (NASH) is the most severe form of non-alcoholic fatty liver disease (NAFLD) and supposed as a potential precursor of HCC.28 16 weeks after HFD feeding, fasting serum glucose and insulin levels were significantly decreased in Mat2a LKO mice." (PMID 35729157, 2022). "Mice lacking B1Rs display an improvement on leptin and insulin sensitivity and are protected from non-alcoholic fatty liver disease (NAFLD) after a high-fat diet treatment." (PMID 36514072, 2022). "Conversely, a molar ratio greater than 2.0 leads to nonalcoholic fatty liver disease or steatohepatitis and disrupted insulin signaling; however, in our VDD model, we do not see nonalcoholic fatty liver disease or steatohepatitis." (PMID 34673019, 2021).
non-alcoholic fatty liver disease (continued). "Among those highly significant pathways, AMPK signaling pathway, PPAR signaling pathway, nonalcoholic fatty liver disease (NAFLD), insulin resistance, insulin signaling pathway, regulation of lipolysis in adipocytes, adipocytokine signaling pathway, and fatty acid biosynthesis are noteworthy." (PMID 33383883, 2020). "However, under conditions of nonalcoholic fatty liver disease and nonalcoholic steatohepatitis, PPAR-γ was obviously overexpressed in the liver and correlated with insulin sensitivity." (PMID 30611282, 2019). "Another ingredient from flex hainanensis Merr., the triterpenoid-rich fraction (TF) had potential ability to protect liver against non-alcoholic fatty liver disease (NAFLD) by regulating lipids metabolism and alleviating insulin resistance, inflammation and oxidative stress in NAFLD murine model." (PMID 29867454, 2018). "Studies show that PCOS is frequently associated with insulin signaling, PI3K-Akt Signaling Pathway, FoxO 1 Signaling, and non-alcoholic fatty liver disease (NAFLD), but the underlying mechanisms are not clear." (PMID 30181771, 2018). "In addition, alpha-lipoic acid has been shown to increase AMPK phosphorylation in liver cells, thus preventing the insulin-stimulated release of SREBP-1c and the development of non-alcoholic fatty liver disease." (PMID 28715446, 2017). "In conclusion, zerumbone improves insulin sensitivity, decreases lipogenesis, and increases lipid oxidation in the liver of HFD-fed hamsters, implying a potential application in the treatment of nonalcoholic fatty liver disease." (PMID 24223615, 2013). "The results show that a moderately low-carbohydrate diet may help to decrease the amount of fat in the liver, increase lean body mass, and improve insulin sensitivity in children with non-alcoholic fatty liver disease without calorie restriction." (PMID 40525060, 2025). "Notably, some of the closely associated Kyoto encyclopedia of genes and genomes (KEGG) pathways were “regulation of lipolysis in adipocytes”, “citrate cycle (TCA cycle)”, “non-alcoholic fatty liver disease (NAFLD)”, “oxidative phosphorylation” and “Insulin signaling pathway”." (PMID 38347496, 2024). "Moreover, in Cretan patients with non-alcoholic fatty liver disease (NAFLD), 6 g/day Spirulina (Greek production) supplementation for six months led to a significant reduction in the HOMA-IR index, a measure representing an enhancement in insulin sensitivity." (PMID 38474769, 2024). "This study aimed to explore relationships between long-chain saturated fatty acids (LSFAs) and nonalcoholic fatty liver disease (NAFLD) in patients with type 2 diabetes (T2D); and whether insulin action had an interactive effect with LSFAs on NAFLD progression." (PMID 36568120, 2022). "It has also been highlighted that KD plays a role in treating nonalcoholic fatty liver disease (NAFLD) by lowering hunger and concurrently decreasing carbohydrate consumption, owing to two separate pathways, which include the general reduction of body weight and the modulation of insulin levels." (PMID 35276979, 2022). "The presence of non-alcoholic fatty liver disease (NAFLD, p = 0.028), serum gamma-glutamyl transferase (GGT) levels (p = 0.009), fatty liver index (FLI, p = 0.018) and the triglyceride glucose index, a surrogate marker of insulin resistance (TyG, p < 0.001), were higher in MetS+ individuals." (PMID 35216509, 2022). "Lipotoxicity drives the development of non-alcoholic fatty liver disease (NAFLD) by inducing a cascade of events including: hepatocellular death; activating Kupffer cells and an inflammatory response; and impaired insulin signaling; ultimately resulting in hepatic insulin resistance." (PMID 27128935, 2016).
sarcopenia (406 papers, 2009 to 2026). Progressive decline in muscle mass due to aging which results in decreased functional capacity of muscles. "Secondary outcomes include change in sarcopenia status, measured using a computerized tomography (CT) scan and sarcopenia-associated muscle biopsy-driven biomarkers (myokines and insulin pathway markers)." (PMID 41210271, 2025). "Fetuin-A, a systemic calcification inhibitor, induces a pro-inflammatory milieu by polarizing M1 macrophages in WAT, generating ROS and reducing insulin sensitivity, which combined with other pro-inflammatory cytokines causes the development of sarcopenia." (PMID 39852400, 2025). "Research has extensively examined hormones, including insulin signaling, inflammatory pathways, and impaired proteostasis, as potential risk factors for sarcopenia." (PMID 39764565, 2025). "Lower levels of physical activity result in reduced glucose uptake by muscles, while sarcopenia, the age-related loss of muscle mass, diminishes the body’s ability to dispose of glucose in response to insulin stimulation." (PMID 40444231, 2025). "This dual effect contributes to the regulation of muscle and hepatic insulin sensitivity, thereby potentially delaying the progression of sarcopenia and reducing the risk of falls." (PMID 40504826, 2025). "Among those chronic diseases, MAFLD is reported to be connected with sarcopenia, as both share multiple pathogenic mechanisms, such as insulin resistance and cytokine release imbalance." (PMID 40429815, 2025). "Secondary outcomes include sarcopenia, measured using dual-energy x-ray absorptiometry scans and sarcopenia-associated muscle biopsy-driven biomarkers (myokines and insulin pathway markers)." (PMID 41210271, 2025). "In older adults, age-related skeletal muscle dysfunction—characterized by mitochondrial impairment, metabolic dysregulation, inflammation, and sarcopenia—leads to reduced insulin sensitivity and is a key mechanism underlying insulin resistance in the elderly." (PMID 40453581, 2025). "Even though the mechanisms linking genetic PAM deficiency to sarcopenia need further study, the most likely mechanism, based on available data, is the reduced secretion of insulin." (PMID 39137152, 2025). "Additional research will be needed to further assess other models of atrophy/sarcopenia to determine the relationship between insulin resistance, BCAA utilization, and loss of skeletal muscle." (PMID 40422898, 2025). "Reduction in lean mass is not only detrimental in that it increases the risk of sarcopenia but because skeletal muscle has a critical role in regulating insulin sensitivity and glucose homeostasis." (PMID 40639664, 2025). "Sarcopenia and muscle wasting: Common in advanced COPD, sarcopenia reduces physical activity, exacerbates insulin resistance, and heightens the risk of metabolic dis-eases." (PMID 40290050, 2025). "The demand for insulin typically follows the duration and severity of illness, which are independently related to the risk of sarcopenia." (PMID 40870444, 2025). "The net effect of insulin therapy on T2D sarcopenia risk is complex and adverse compared to newer agents, despite its anabolic properties." (PMID 40870444, 2025). "Novel metabolomic approaches have identified specific lipid signatures associated with sarcopenia, including elevated ceramides and diacylglycerols that indicate lipotoxicity and insulin resistance in muscle tissue." (PMID 41220691, 2025). "Sarcopenia affects physical mobility and causes metabolic dysfunctions, such as energy homeostasis, heat regulation, insulin sensitivity, and amino acid metabolism." (PMID 38293722, 2024). "Beyond muscle physiology, vitamin D levels are implicated in modulating inflammation and insulin secretion, factors that are also recognized to influence sarcopenia onset." (PMID 39633310, 2024).
sarcopenia (continued). "In skeletal muscle, physical inactivity has catabolic effects and can lead to decreased lean muscle mass, while exercise is known to induce insulin sensitization and promote muscle protein synthesis, reducing the risk of sarcopenia." (PMID 38474786, 2024). "In a cross-sectional study of older Chinese females aged over 50 years, lower-insulin was associated with sarcopenia and risk factors for low muscle mass." (PMID 39839409, 2024). "Excessive fat mass associated with aging fosters muscle insulin resistance and consequently leads to sarcopenia." (PMID 38612998, 2024). "Conversely, metabolic hormones such as insulin growth factor 1, insulin, and adiponectin are correlated with a reduced risk of sarcopenia." (PMID 39186818, 2024). "The effect of insulin treatment remains controversial; in cross-sectional designs, the use of insulin shows an association with the development of sarcopenia." (PMID 38131980, 2023). "It is also notable that exercise training programs, an established method to improve insulin resistance, improve both phosphate removal and reduce the risk of sarcopenia in dialysis patients." (PMID 36994079, 2023). "Skeletal muscle mass, a diagnostic parameter of sarcopenia, accounts for almost half of body weight and is vital in various metabolic pathways (i.e., insulin resistance, arterial stiffness, and oxidative stress)." (PMID 36545275, 2023). "Among middle-aged and older adults of multiple ethnicities in western China, we found that higher AST/ALT and lower INS*PA levels are associated with an increased prevalence of sarcopenia." (PMID 35370985, 2022). "Some studies have shown that low-level physical activity is a risk factor for sarcopenia, which can induce anabolic resistance, protein synthesis after meals, insulin sensitivity, and leg muscle mass in older adults." (PMID 36363519, 2022). "Sarcopenia was associated with lower fasting insulin (p < 0.05) in comparison to non-sarcopenia and possible sarcopenia in the whole exploratory sample of pre-frail/frail elderly." (PMID 36482911, 2022). "There is an age-related decrease in insulin-mediated peripheral glucose utilization and suppression of proteolysis that are associated with sarcopenia." (PMID 36482911, 2022). "For example, a reduced proportion of oxidative slow-twitch type I fibers is associated with lower insulin sensitivity in the diabetic muscle and muscle atrophy, e.g., age-related sarcopenia is progressing in a fiber type-specific manner." (PMID 35780170, 2022). "Excess weight and central adiposity have been suggested to exacerbate the risk of sarcopenia due to increased infiltration of fat into muscles and inflammation and insulin resistance." (PMID 35648298, 2022). "Sarcopenia is a progressive and generalized skeletal muscle disorder caused by various factors such as systemic inflammation, insulin resistance, and myokine and adiponectin dysregulation." (PMID 35256716, 2022). "Among these risk factors, serum AST/ALT ratio and INS*PA product have stronger effects on sarcopenia." (PMID 35370985, 2022). "Studies have shown that decreases in age-related hormones (e.g., insulin, growth hormone, insulin-like growth factor, testosterone) are strongly associated with the development of sarcopenia." (PMID 36091250, 2022). "In multivariable logistic regression models, sarcopenia was independently associated with low insulin (p < 0.05)." (PMID 36482911, 2022). "The levels of insulin were borderlinely or significantly inversely associated with the presence of sarcopenia in the exploratory sample and the validation sample." (PMID 36482911, 2022). "Empirical evidence suggests the critical role of sufficient insulin in promoting protein synthesis, maintaining muscle function, and preventing muscle mass loss and sarcopenia." (PMID 36482911, 2022). "The top tertile of fasting insulin was associated with lower risk of sarcopenia relative to the bottom tertile, with an OR of 0.297." (PMID 36482911, 2022).